TMEM179 (transmembrane protein 179)
Synonyms: C14orf90; TMEM179A; FLJ42486
Tractability: Antibody: UniProt predicts a signal peptide or a membrane-spanning region.
Gene: Protein-coding gene on chromosome 14 (104,474,678 to 104,605,647, reverse strand). Ensembl gene ENSG00000258986.
Subcellular location: Membrane
Subcellular location (Human Protein Atlas): Mitochondria
Gene Ontology:
Cellular component: membrane
Genetic constraint (gnomAD): Loss-of-function variants: 17 observed, 17.43 expected, observed/expected ratio (o/e) 0.98, 90% interval 0.67 to 1.46. The upper end of that interval is the gene's LOEUF score, 1.46, which puts it in group 6 of 6, group 1 being the genes least tolerant of losing a copy. Missense variants: 265 observed, 278.6 expected, observed/expected ratio (o/e) 0.95, 90% interval 0.86 to 1.05. Synonymous variants: 127 observed, 123.99 expected, observed/expected ratio (o/e) 1.02, 90% interval 0.89 to 1.19.
Homologues: Orthologues: chimpanzee TMEM179 (99% identical), macaque TMEM179 (99% identical), dog TMEM179 (95% identical), mouse Tmem179 (94% identical), rat Tmem179 (94% identical), pig TMEM179 (93% identical), zebrafish TMEM179 (66% identical), zebrafish tmem179aa (63% identical), tropical clawed frog tmem179 (62% identical), Drosophila melanogaster CG13603 (27% identical).
Diseases named in the same sentence as TMEM179 in open-access papers:
TMEM179 is named in the same sentence as 5 diseases in open-access papers, as found by Europe PMC text mining. Sharing a sentence is not in itself a finding about the gene and the disease. The quoted sentences say what the papers report.
liver cancer (1 paper, 2021). An epithelial or non-epithelial malignant neoplasm that arises from the liver. "We found that 6 mRNA expressions were significantly different (P<0.05), including GBP6 (guanylate binding protein), TMEM (transmembrane protein), CTCFL (liver cancer marker gene), KRT5 (keratin 5), LY6D (lymphocyte antigen) and TMEM179 (transmembrane protein)." (PMID 34714841, 2021).
multiple myelomas (1 paper, 2009). "TMEM179 is located on human 14q32.33 approximately 1 Mb upstream from the immunoglobulin heavy chain (IGH) region, which has been involved in translocations in multiple myelomas and plasma cell leukemias." (PMID 19630942, 2009).
TMEM179 also shares sentences with these, for which no sentence is quoted: Anxiety (1 paper); depression (1); plasma cell leukemia (1).